VWF (von Willebrand factor)
Diseases named in the same sentence as VWF in open-access papers (continued):
Sharing a sentence is not in itself a finding about the gene and the disease.
endothelial dysfunction (continued). "The higher VWF levels may reflect the aggravated endothelial dysfunction related to prevalent cardiovascular risk factors in MASH patients." (PMID 40884085, 2025). "Furthermore, in COVID-19 infection, elevated vWF levels are closely associated with endothelial dysfunction and serve as a predictive marker for adverse outcomes." (PMID 40226433, 2025). "Consequently, our current findings indicate that individuals in the high-risk clusters are at greater risk for premature death due to advanced endothelial dysfunction, as indicated by high vWF levels in this subgroup." (PMID 39175055, 2024). "Besides this, vWF is widely recognized as a marker of endothelial dysfunction, an important pathophysiological process underlying cardiovascular disease in individuals with prediabetes and diabetes." (PMID 39175055, 2024). "Additionally, PAI-1, like vWF, is an established marker of endothelial dysfunction, confirming the association between glycemic disorders, endothelial dysfunction, and cardiovascular disease." (PMID 39175055, 2024). "The prothrombotic shift in infected lungs was revealed by increased expression of the coagulation cascade mediators TF, PLAT, PAI-1, THBD, and vWF associated with endothelial dysfunction as shown through the upregulated expression of ESAM, CD106, CD201, VEGF-A, and VEGFR-2." (PMID 38474396, 2024). "The probable mechanisms of this are both the underlying endothelial dysfunction, which may increase von Willebrand factor levels, as well as the thrombogenicity of von Willebrand factor itself." (PMID 36009558, 2022). "The association between VWF: Ag levels and coronary artery disease is well-established, suggesting that endothelial dysfunction may contribute to its pathogenesis." (PMID 36684571, 2022). "The development of endothelial dysfunction in Ang II-treated mice was associated with endothelial inflammation as evidenced by an increased endothelial expression of vWF, whereas concomitant administration of dabigatran prevented the increase in vWF expression." (PMID 34445374, 2021). "vWF is a circulating adhesive glycoprotein secreted by endothelial cells and platelets and its plasma levels have been found elevated in vasculitis, inflammation, aging, and diabetes, all conditions associated with endothelial dysfunction." (PMID 34235394, 2021). "Although whether the increased plasma concentration of vWF is a cause or consequence of endothelial dysfunction remains unclear, one study showed that reduced vWF overexpression can protect endothelial cells from harmful stimulation from high Angiotensin II." (PMID 34777257, 2021). "Furthermore, endothelial dysfunction causes overproduction of coagulation-promoting factors like von Willebrand factor (VWF) and plasminogen activator inhibitor-1 (PAI-1), which is also further induced by Ang II." (PMID 33800470, 2021). "VWF is a circulating adhesive glycoprotein that is secreted by endothelial cells and platelets and its levels is elevated in vasculitis, inflammation, aging, and diabetes, conditions that are all associated with endothelial dysfunction." (PMID 32660065, 2020). "Importantly, choroidal thinning was positively associated with markers of endothelial dysfunction (ET-1) and systemic inflammation (vWF)." (PMID 33080821, 2020). "Some reports have associated menopause, viral load and endothelial dysfunction with increased vWF." (PMID 32049963, 2020). "We hypothesized several possible mechanisms for this phenomenon, including impaired protein synthesis in the liver or endothelial dysfunction associated with direct chemotherapy toxicity and consumption by increased vWF substrates." (PMID 33292287, 2020). "Endothelial dysfunction in COVID-19 is linked to hypercoagulability as indicated by increased fibrinogen and von Willebrand factor levels as well as elevated numbers of activated platelets and their complexes with leukocytes together with abnormal coagulation parameters." (PMID 33392206, 2020).
endothelial dysfunction (continued). "Altogether, these findings support the proposal that elevated VWF levels and endothelial dysfunction are associated with nephropathy in DM1, and might be useful to predict the development of renal disease in these patients." (PMID 26168189, 2015). "This method might be useful in the monitoring of VWF : Ag in patients that are at a high risk of vascular event related to endothelial dysfunction." (PMID 25759835, 2014). "However, cfDNA levels were correlated to levels of hsCRP (P = 0.0497) and vWF (P = 0.0005), which have previously been shown to reflect endothelial dysfunction and associate with elevated cardiovascular risk." (PMID 25371664, 2014). "Interestingly, in this patient group vWF was a predictor of Ks, indicating novel associations linking endothelial dysfunction with fibrin clot properties measured ex vivo." (PMID 23086579, 2013). "Finally, another study has shown that high fibrinogen levels are linked in hyperthyroidism to an elevation of von Willebrand factor and to altered platelet plug formation as an direct index of endothelial dysfunction." (PMID 19014658, 2008). "Additionally, at the one-year follow-up, we found lower levels of factor IX (p = 0.002) and higher levels of VWF (p = 0.006) associated with higher levels of NT-proBNP, underscoring the involvement of both hemostatic imbalance and persistent endothelial dysfunction." (PMID 40725101, 2025). "In addition to coagulation markers, endothelial dysfunction may underlie the increased risk of thromboembolism in COVID-19 as both vWF activity and vWF antigen are increased in COVID-19 ARDS compared to non-COVID-19 ARDS." (PMID 33195487, 2020). "In addition to the changes in fibrinolytic function, prothrombotic effects occur due to endothelial dysfunction due to decreased release of nitric oxide and prostacyclin, upregulation/expression of tissue factor and von Willebrand factor (VWF), and loss of the glycocalyx." (PMID 31121897, 2019). "In this cross sectional study in an elderly population we could demonstrate that the presence of permanent or persistent AF were associated with endothelial dysfunction, assessed by increased levels of vWF, and even more pronounced by the levels of ADMA and the ratio of L-arginine/ADMA." (PMID 28352406, 2012). "In contrast, vWF antigen and activity further increased, indicating persistent endothelial dysfunction." (PMID 41595788, 2026). "The pro‐thrombotic state characteristic of diabetes, driven by endothelial dysfunction, increased expression of von Willebrand factor (vWF) and platelet activation, accelerates atherogenesis and plaque instability." (PMID 41405560, 2026). "Altered shear stress, turbulent flow, and endothelial dysfunction promote thrombus formation and modulate systemic hemostasis via platelet activation and the von Willebrand factor-ADAMTS13 axis." (PMID 41977327, 2026). "Possible explanations, such as endothelial dysfunction, platelet activation together with a rise of Von Willebrand factor, and hypomagnesemia-induced vasospasm, have been discussed." (PMID 40723253, 2025). "In experimental models, endothelial knockdown of vWF suppressed Ang II‐induced endothelin‐1 expression and reduced NOX‐mediated oxidative stress, implicating vWF in endothelial dysfunction during AF." (PMID 40765025, 2025). "Acute hyperhomocysteinemia increased markers of endothelial dysfunction (vWF) and platelet activation (fibrinogen binding) in SLE patients.PAI-1 levels increased significantly only in controls.FMD was not significantly impaired post-loading in either group." (PMID 41179568, 2025). "The inflammatory response in COVID-19 enhances endothelial dysfunction and hypercoagulability, which are key drivers of thrombosis, as evidenced by elevated markers such as vWF and CNAs." (PMID 41311551, 2025).
endothelial dysfunction (continued). "De novo exposure of naïve HUVECs to hyperglycemic conditions replicated these findings and further induced markers of endothelial dysfunction such as von Willebrand factor (vWF), CCL2, ICAM-1, and the anti-apoptotic protein BCL2." (PMID 41020807, 2025). "Elevated levels of the markers of endothelial dysfunction, including endothelin-1, tissue plasminogen activator, fibronectin, and particularly von Willebrand factor, have been observed in patients with PRES." (PMID 40641529, 2025). "Alterations in the production and availability of endothelial-derived nitric oxide (NO), endothelin (ET), and von Willebrand factor (vWF) are referred to as endothelial dysfunction and are considered a critical initiating factor in coronary artery disease." (PMID 40291842, 2025). "As the test is carried out using blood plasma, it does not consider the number or the function of platelets, thus also excluding the role played by elevated von Willebrand factor (vWF) levels and the impact of endothelial dysfunction." (PMID 40429533, 2025). "High vWF levels had predictive values for screening patients with T2DM accompanied by endothelial dysfunction." (PMID 40406484, 2025). "In contrast, vWF antigen (CV = 19.4%) and sE-selectin (CV = 56.5%) showed more consistent profiles, potentially indicating more stable patterns of endothelial dysfunction." (PMID 40430232, 2025). "ANP is a key regulator of fluid balance and cardiac preload, while vWF is a marker of endothelial dysfunction, which is relevant given the vascular injury and thrombotic risk associated with both AMI and CKD." (PMID 41049335, 2025). "We further investigated ANGPT2 and VWF, two important endothelial dysfunction markers in multiple inflammatory disorders." (PMID 40894883, 2025). "The vWF is a glycoprotein primarily secreted by vascular endothelial cells and released in response to endothelial injury, making it a widely used marker of endothelial dysfunction." (PMID 41007843, 2025). "Different mechanisms are involved in the prothrombotic state of COVID-19 patients, including a dysregulated renin–angiotensin–aldosterone system (RAAS), endothelial dysfunction, elevated von Willebrand factor (vWF), and a dysregulated immune response." (PMID 40226433, 2025). "Future clinical trials evaluating endothelial-targeted therapies in ACLF should consider stratifying patients based on baseline levels of endothelial dysfunction markers, such as vWF and ADAMTS13." (PMID 40429533, 2025). "Vascular pathology is a recurrent and prominent feature in infected NHPs, where they exhibit CD61+ platelet aggregation, microhemorrhages, and von Willebrand factor deposition, reflecting endothelial dysfunction and impaired perfusion." (PMID 41305454, 2025). "Levels of tPA are often decreased, while von Willebrand factor (vWF) antigen levels are elevated, indicating endothelial dysfunction." (PMID 41150738, 2025). "Regarding endothelial dysfunction, we know that von Willebrand factor (vWF), a marker of endothelial damage, is often elevated in patients with solid and/or hematological malignancies." (PMID 40944099, 2025). "Concurrently, endothelial dysfunction and inflammation catalyze the release of von Willebrand factor, which contributes to platelet adhesion and subsequent thrombus formation." (PMID 38818123, 2024). "The correlation between von Willebrand factor and neutrophil elastase supports our notion that neutrophil elastase is responsible for endothelial dysfunction in preeclampsia." (PMID 39301340, 2024). "In this study, the expression of endothelial dysfunction biomarkers such as vWF and ET-1, and CD11b and MPO double positive cells increased when lung strain reached 1.5, indicating that the UPLS provoked the inflammation." (PMID 39845800, 2024).
endothelial dysfunction (continued). "Although these results are still preliminary, they establish the platform potential to recapitulate TTP’s abnormal vWF manifestation and coagulation using blood from healthy volunteers, as well as other pathologies that involve endothelial dysfunction." (PMID 39203639, 2024). "This molecular response, in turn, fostered endothelial dysfunction, senescence, NF-κB activation, inflammation, platelet adhesion and aggregation, von Willebrand factor secretion, and thrombin generation." (PMID 38448675, 2024). "Studies have shown that individuals with CD exhibit signs of endothelial dysfunction, including impaired flow-mediated dilation and elevated levels of endothelial activation markers such as von Willebrand factor and soluble intercellular adhesion molecule-1." (PMID 39150613, 2024). "A correlation between NLR, vWF, and neutrophil elastase and endothelial dysfunction in preeclampsia (PE) has also been established." (PMID 39301340, 2024). "Von Willebrand factor (vWF), primarily synthesized by endothelial cells, is a key biomarker of endothelial dysfunction." (PMID 39872596, 2024). "Hypoxia-induced insulin resistance is promoted by the procoagulant molecule von Willebrand factor (vWF), which is produced more frequently during endothelial dysfunction and a prothrombotic state." (PMID 39252788, 2024). "Frailty has been associated with endothelial dysfunction, as evidenced by the following serum markers: intercellular adhesion molecule 1 (ICAM-1), endothelin 1 (ET-1), von Willebrand factor (vWF), plasma thrombomodulin, and asymmetric dimethylarginine (ADMA)." (PMID 39335518, 2024). "The biomarkers for endothelial dysfunction, such as VWF, factor VIII, and soluble thrombomodulin levels, were significantly elevated in convalescent COVID-19 patients compared with those for the controls." (PMID 39199353, 2024). "The serum NO concentrations were lower in PE patients and endothelial dysfunction markers (NE and von Willebrand factor {vWF}) were markedly increased in PE patients." (PMID 39301340, 2024). "There is evidence of endothelial dysfunction in diabetic patients based on elevated vWF plasma levels, decreased prostacyclin and plasminogen activator levels." (PMID 39040847, 2024). "Higher levels of vWF in the plasma indicate endothelial dysfunction, which increases the likelihood of developing atherosclerosis and thrombosis." (PMID 38397876, 2024). "Conversely, AF worsens CAD by inducing endothelial dysfunction and systemic inflammation, driven by reduced nitric oxide availability and increased von Willebrand factor expression, which lead to atherosclerotic plaque instability and ischemia." (PMID 39872596, 2024). "Resveratrol has been found to enhance total antioxidant ability and reduce levels of endothelial dysfunction biomarkers, such as vWF, ICAM‐1, and caspase 3 in endothelial cells and umbilical arteries from patients with preeclampsia." (PMID 39040847, 2024). "Von Willebrand factor (VWF) is elevated in insulin-resistant states, suggesting that insulin resistance induces endothelial dysfunction." (PMID 39199353, 2024). "In the same way, the role of vWF as a marker of endothelial dysfunction in predicting prognosis was studied in anticoagulated AF patients." (PMID 38397876, 2024). "Biomarkers such as CRP and IL-6 play a role in promoting the production of tissue factor and von Willebrand factor (vWF), which worsen endothelial dysfunction and enhance coagulation while impairing fibrinolysis." (PMID 39588448, 2024). "Factors, such as endothelial dysfunction, platelet activation, and increased von Willebrand factor (VWF) levels contribute to the hypercoagulable state, increasing the risk of thrombotic events." (PMID 37712883, 2024). "One of the key genes was VWF, an acceptable biomarker of endothelial dysfunction in vascular diseases." (PMID 38987722, 2024).
endothelial dysfunction (continued). "Early studies have found that VWF is elevated in patients with ACLD and linked this observation to endothelial dysfunction, which seemed to be related to endotoxemia arising from pathological bacterial translocation." (PMID 37605068, 2023). "Elevated plasma levels of VWF have been reported in various inflammatory conditions where endothelial dysfunction has a prominent role, such as autoimmune and neoplastic disorders." (PMID 36765638, 2023). "Multiple correlations were found between several PCC symptoms and markers of endothelial dysfunction (endothelin-1 and von Willebrand factor) and systemic inflammation (Interleukin-1 Receptor antagonist)." (PMID 37868959, 2023). "An increased von Willebrand factor mediates the adhesion of activated platelets by forming platelet aggregates and inducing platelet-endothelial interactions, which are vital in endothelial dysfunction and microvascular thrombosis formation." (PMID 38049548, 2023). "On the other hand, mean VWF : Ag concentrations were still elevated in 79.2% of participants suggesting endothelial dysfunction." (PMID 37868959, 2023). "The expression levels of ICAM-1, VCAM-1, vWF, and ET-1 in CiGEnCs were measured to evaluate the degree of endothelial dysfunction." (PMID 37188751, 2023). "Endothelial dysfunction induces the secretion of coagulation factors (VWF and TM) the expression of cell adhesion molecules (ICAM, VCAM) and pro-inflammatory cytokines (TNFa, IFNγ, etc.), while it also activates the complement system." (PMID 36765638, 2023). "They exposed both ECs in uremic sera that caused endothelial dysfunction by increasing VCAM1, ICAM1, and ROS production, and reducing NOS3 and von Willebrand factor (VWF) expression, platelet adhesion, and phosphorylation of p38MAPK and p42/44." (PMID 37841935, 2023). "As reported in the literature, endothelial dysfunction biomarkers such as vWF and PAI-1 are increased in COVID-19 patients compared to healthy subjects." (PMID 38188630, 2023). "Though some evidence suggests plasma vWF can function as a biomarker of endothelial dysfunction, considerable inconsistencies remain among clinical studies." (PMID 37685924, 2023). "Endothelial dysfunction induced by various stimuli results in secretion of VWF from Weibel–Palade bodies to systemic circulation." (PMID 36765638, 2023). "During the COVID-19 pandemic, the vWF became a specific marker of endothelial dysfunction, helpful in determining the severity of the disease." (PMID 37554121, 2023). "Hemodynamic changes and endothelial dysfunction were shown to increase levels of von Willebrand factor (VWF), platelet reactivity, and thrombin generation in the Fontan circulation." (PMID 36769887, 2023). "Von Willebrand factor is stored in endothelial cells and is released in response to endothelial damage and has therefore been proposed as a marker of endothelial dysfunction." (PMID 36808666, 2023). "Endothelial dysfunction, spiking of von Willebrand factor (vWF), and excessive cytokine signaling result in coagulopathy associated with substantial activation of plasmatic clotting factors." (PMID 36611985, 2023). "In this context, our study is limited by not providing any intrahepatic readouts (e.g., histological data) linking VWF biomarker levels to intrahepatic endothelial dysfunction." (PMID 37605068, 2023). "Previous studies indicated a link between elevated VWF levels and fundamental pathological features of cirrhosis such as endothelial dysfunction and PH; moreover, it constitutes a key feature of the hypercoagulability accompanying liver disease progression." (PMID 37605068, 2023). "Lastly, VWF: Ag and VWF: Ac were assessed as markers of endothelial dysfunction in this study and they were found to be elevated in CTEPH patients compared to controls." (PMID 35626393, 2022).